LRP2 (LDL receptor related protein 2)
Diseases named in the same sentence as LRP2 in open-access papers (continued):
Sharing a sentence is not in itself a finding about the gene and the disease.
breast carcinoma (6 papers, 2018 to 2024). "Low LRP2 was also associated with shorter overall survival in the KMplotter database (lower quartile cutoff Kaplan–Meier analysis, HR = 0.64, p < 0.0001), which is an integrated database of breast cancer gene-expression data." (PMID 36980716, 2023). "We further evaluated the relationship between LRP2 expression and molecular subtypes or signatures related to differentiation in breast cancer, mesothelioma, and thyroid cancer." (PMID 36980716, 2023). "Two studies support the role of LRP2 in mediating endocytic uptake of vitamin D (in complex with vitamin D binding protein) and in the activation of vitamin D receptor signaling in breast cancer cells." (PMID 36980716, 2023). "Next, immunohistochemical analysis of 12 luminal A invasive breast cancer samples was performed using either the monoclonal mouse anti-human LRP2 antibody or the polyclonal rabbit anti-human LRP2 antibody." (PMID 36980716, 2023). "LRP2 expression has been observed in breast cancer cell lines, where LRP2 has been suggested to facilitate vitamin D uptake." (PMID 36980716, 2023). "Single-cell RNA sequencing data from clear cell renal cell carcinoma and breast cancer, two cancer types with high expression of LRP2, revealed that LRP2 expression is restricted to epithelial cancer cells (and residual normal epithelial cells) in the tumor microenvironment." (PMID 36980716, 2023). "Our result implies that LRP2 is also a favorable prognostic factor in premenopausal breast cancer." (PMID 34575612, 2021). "The low expression of LRP2 in some breast cancers leads to a decrease in the activation of its nuclear receptor VDR, which promotes the proliferative process of breast cancer." (PMID 38037058, 2023). "Information on LRP2 in breast cancer is very limited, and its prognostic role was not yet investigated." (PMID 34575612, 2021). "In line with this, we find it tempting to speculate that LRP2 also plays a role in this context and that the presence or absence of LRP2 in breast cancer cells would have an important impact on vitamin D homeostasis and receptor signaling." (PMID 36980716, 2023). "However, the 7 genes matching this description (Clasrp, Cyp3a44, Gpr18, Lrp2, Map1b, Spen, and Ttn), are neither known breast cancer or pan‐cancer driver genes nor directly involved with the activation of MAPK/ERK signaling." (PMID 35398967, 2022).
holoprosencephaly (6 papers, 2014 to 2023). Holoprosencephaly (HPE) is a complex brain malformation resulting from incomplete cleavage of the prosencephalon, occurring between the 18th and 28th day of gestation, and affecting both the forebrain and face, which results in neurological manifestations and facial anomalies of variable severity. "LRP2 is expressed in the neuroepithelium and loss of LRP2 in the knockout mouse model results in holoprosencephaly (fusion of the forebrain) and buphthalmia (the overgrowth of the eye globe)." (PMID 34445520, 2021). "The positive role of Ulk4 in Shh signaling could explain why elevated expression of Ulk4 in certain genetic background could suppress the heart outflow tract defects and holoprosencephaly caused by partially reduced Shh signaling activity in LRP2-deficient mice." (PMID 38096226, 2023). "LRP2 is essential for brain development, as knock-out mice exhibit holoprosencephaly and Lrp2-mutant mice have abnormal cortical axon development." (PMID 25158045, 2014).
vitamin D deficiency (6 papers, 2011 to 2024). A nutritional condition produced by a deficiency of VITAMIN D in the diet, insufficient production of vitamin D in the skin, inadequate absorption of vitamin D from the diet, or abnormal conversion of vitamin D to its bioactive metabolites. "On the other hand, a deletion of megalin (LRP2) 600-kDa transmembrane glycoprotein, which functions as an endocytic receptor, results in vitamin D deficiency." (PMID 36501134, 2022). "LRP2 knockout mice showed severe vitamin D deficiency and bone disease, indicating the involvement of LRP2 in the preservation of vitamin D metabolites and delivery of the precursor to the kidney for the generation of 1α,25(OH)2D3." (PMID 22174918, 2011). "In LRP2 knockout mice, vitamin D deficiency and bone disease were induced by the abnormal urinary excretion of 25OHD3 and DBP." (PMID 22174918, 2011). "Additionally, LRP2 rs2075252 variant has been associated with vitamin D deficiency, while CUBN rs41301097 has been strongly correlated with higher 25(OH)D levels." (PMID 38008818, 2024). "Moreover, individuals with polymorphisms in CYP24A1 (rs2248137) and LRP2 (rs2389557 and rs4667591), coupled with vitamin D deficiency in the second trimester, demonstrated an elevated risk of developing HDP." (PMID 38613027, 2024). "In LRP2 knockout mice, bone disorder and Vitamin D deficiency were found." (PMID 34991478, 2022). "This is the first study examining the potential implication of LRP2 and CUBN gene polymorphisms in OSAS occurrence, in association with vitamin D deficiency." (PMID 38008818, 2024).
buphthalmia (5 papers, 2019 to 2025). "In both cases, membrane-bound Lrp2 is not present to facilitate normal regulation of eye size, and buphthalmia is the result." (PMID 31457013, 2019).
glioma (5 papers, 2020 to 2025). A benign or malignant brain and spinal cord tumor that arises from glial cells (astrocytes, oligodendrocytes, ependymal cells). "The results showed that LRP2 mutations were associated with better prognosis in endometrial cancer (OS, p < 0.001), bladder urothelial carcinoma (OS, p = 0.0061) and brain lower grade glioma (OS, p < 0.0293)." (PMID 35834061, 2022). "MDK resulted in 1 of the top possible mediators of the interaction between glioma cells and oligodendrocytes through its ligand LRP2." (PMID 33155039, 2020). "Bioinformatics analysis using TIMER2.0 and GEPIA 2.0 revealed positive correlations between CLU expression and several genes (BAX, BCL2L1, PRNP, HSPA5, LRP2, TTR, all p < 0.05), suggesting synergistic or antagonistic interactions during glioma development." (PMID 40606578, 2025). "The oncogenic role of MDK, promoting proliferation and pharmacological resistance in glioma, may involve the release of Sonic Hedgehog (SHH) from LRP2 sequestration in oligodendrocytes, thus functioning to activate one of the best-known activators of proliferation and stemness of brain tumors." (PMID 33155039, 2020).
renal cell carcinoma (5 papers, 2017 to 2025). "We show that LRP2 downregulation correlates with poor patient outcome in multiple cancer types, including renal cell carcinoma, mesothelioma, thyroid cancer and invasive breast carcinoma." (PMID 36980716, 2023). "LRP2 has been proposed as a potential target for selective anti-cancer drug delivery, with studies showing that kidney-targeting multimodal micelles and light-chain conjugated nanoparticles can target renal cell carcinoma cells through their interaction with LRP2." (PMID 36980716, 2023). "Higher expression of LRP2 was reported as a favorable prognostic factor in renal cell carcinoma." (PMID 34575612, 2021). "Expression of LRP2 in renal cell carcinoma has been reported previously." (PMID 29088295, 2017). "The interpretable models identified genes such as LRP2 and ACE2 as highly relevant to renal cell carcinoma." (PMID 40373089, 2025).
colon carcinoma (4 papers, 2022 to 2025). "We next investigated the biological processes that might underlie the clinical prognostic significance of CDH17 and LRP2, respectively, in stage II colon cancer." (PMID 36612154, 2022). "Although arising outside the eye, colon cancer data further underscore the tissue-specificity of LRP2′s role in tumor biology." (PMID 41374987, 2025). "We found that the LRP2 level was elevated in colon cancer, but its correlation with tumorigenesis is still unknown." (PMID 38045683, 2023). "The results showed that the expression levels of ACSL6, CYP19A1, LRP2, OSBPL3 and SLCO1A2 were considerably increased, while those of ACOX1, FABP4, PLAAT5, PPARGC1A and TNFAIP8L3 were decreased in colon cancer." (PMID 38045683, 2023). "Collectively, we screened the six LMGs including CYP19A1, FABP4, LRP2, SLCO1A2, PPARGC1A and ALOXE3, and constructed a signature to predict prognosis and immunotherapeutic response in colon cancer, which was extendedly and externally validated." (PMID 37055842, 2023). "Secondly, we studied the expression and pathophysiological significance of CYP19A1 in vitro and in vivo, and further studies are needed on other LMGs including FABP4, LRP2, SLCO1A2, PPARGC1A and ALOXE3 in colon cancer." (PMID 37055842, 2023). "Here we integrated CYP19A1, FABP4, LRP2, SLCO1A2, PPARGC1A and ALOXE3 with clinicopathological information of patients to construct a prognostic nomogram in colon cancer." (PMID 37055842, 2023).
gastric cancer (4 papers, 2017 to 2022). A primary or metastatic malignant neoplasm involving the stomach. "In gastric cancer, LRP2 was indicated to be a mutated gene by using next-generation sequencing technology." (PMID 35190739, 2022). "Somatic mutations in LRP2 have been identified in gastric cancer." (PMID 36727052, 2022).
glaucoma (4 papers, 2012 to 2025). Increased pressure in the eyeball due to obstruction of the outflow of aqueous humor. "Through literature review, several key glaucoma-related genes were identified, including MYOC, TBK1, COL1A1, COL1A2, FOXC1, LRP2, OPTN, and TEK." (PMID 40808675, 2025). "Interestingly, these glaucoma-related genes like MYOC, TBK1, COL1A1, COL1A2, FOXC1, LRP2, and TEK also showed significant differential expression in RCC tissues." (PMID 40808675, 2025).
Intellectual disability (4 papers, 2020 to 2023). "Moreover, LRP2 polymorphisms were recently linked to non-syndromic cognitive impairment and intellectual disabilities." (PMID 33225275, 2020). "In addition, mutations in LRP2 may contribute to Stickler syndrome and autosomal recessive non-syndromic intellectual disability." (PMID 34872573, 2021).
pancreatic cancer (4 papers, 2013 to 2019). "The LRP2 rs3944004 minor homozygote was significantly associated with an almost doubling in pancreatic cancer risk (GG versus TT, OR = 1.93; 95% 1.25–2.97)." (PMID 23826131, 2013). "LRP2 knockout mice exhibit vitamin D and estrogen deficiency but no studies have evaluated if LRP2 modifies the association between vitamin D and pancreas cancer." (PMID 23826131, 2013). "SNPs near the VDR (rs2239186), LRP2 (rs4668123), CYP24A1 (rs2762932), GC (rs2282679), and CUBN (rs1810205) genes were the top SNPs associated with pancreatic cancer (p-values 0.008–0.037), but none were statistically significant after adjusting for multiple comparisons." (PMID 25799011, 2015).
COVID-19 (3 papers, 2021 to 2025). A disease caused by infection with severe acute respiratory syndrome coronavirus 2. "Furthermore, with the prevalence of long COVID and persistent cognitive impairment associated with COVID-19, it is important to note that both LRP1 and LRP2 have been shown to endocytose ligands across the blood–brain barrier." (PMID 40349772, 2025). "At maximum extent of ATI (>50% of tubules), KIM-1 was expressed in 27% (3322 of 12,123), whereas NGAL was expressed in 65.7% (6580 of 10,111) of the tubules, including significant coexpression with KIM-1 in 85% of COVID-19 kidneys and with proximal marker LRP2 in 77% of the kidneys." (PMID 34642645, 2021). "The study found that the levels of two important regulators involved in renal tubular reabsorption, megalin (LRP2) and cubilin (CUBN), showed a decreasing trend in the urine of patients with COVID-19." (PMID 36203586, 2022).
cutaneous melanoma (3 papers, 2017 to 2025). A primary melanoma arising from atypical melanocytes in the skin. "Although not directly studied in large ocular melanoma cohorts, research on cutaneous melanoma suggests that tumors can aberrantly acquire LRP2 and depend on it for proliferation and survival." (PMID 41374987, 2025). "We did not observe a significant difference in patient survival when LRP2 expression was examined in cutaneous melanomas in patients." (PMID 29088295, 2017). "Furthermore, these data confirmed mid-to-high LRP2 expression in a subset of cutaneous melanoma (SKCM), which is consistent with our previous study." (PMID 36980716, 2023).
developmental delay (3 papers, 2017 to 2023). "We provide a clinical report of two mono-chorionic twins with LRP2-related disease manifesting developmental delay, autistic features, seizures, proteinuria, and sleep disorders." (PMID 37810913, 2023).
hearing loss (3 papers, 2012 to 2024). "Some of these hearing loss or deafness genes have also been identified as candidate echolocation genes, such as CDH23 and LRP2." (PMID 38672325, 2024). "The importance of elevated intralabyrinthine protein underlying hearing loss is supported by previous studies examining unique perilymphatic proteins that are elevated in CVSs, including μ-Crystallin (CRYM) and low density lipoprotein-related protein 2 (LRP2)." (PMID 23049959, 2012).
Hypertension (3 papers, 2016 to 2022). The presence of chronic increased pressure in the systemic arterial system. "Defects in three of these genes, Slc6a19, Slc4a4, and Lrp2 have been linked to hypertension." (PMID 27462279, 2016).
hyperuricemia (3 papers, 2014 to 2020). An abnormally high level of uric acid. "An interaction between alcohol and the T allele of LRP2 rs2544390 was initially described for serum urate levels in a Japanese cohort with the highest risk of hyperuricaemia in males with TT who consumed five or more drinks per week." (PMID 28566086, 2017).
hypothyroidism (3 papers, 2019 to 2023). Abnormally low levels of thyroid hormone. "LRP2 knockout mice showed hypothyroidism associated with decreased serum Tg and fT4 levels and increased TSH levels." (PMID 37545519, 2023). "LRP2 variant rs3213760 was identified in one patient with RRMS and one family member with hypothyroidism from a type‐B family." (PMID 30900415, 2019). "We also identified a family in which the variants rs3213760 (LRP2) and rs12259370 (CUBN) were present in an individual with hypothyroidism and in no patients with MS." (PMID 30900415, 2019).
Insulin resistance (3 papers, 2014 to 2023). Increased resistance towards insulin, that is, diminished effectiveness of insulin in reducing blood glucose levels. "Of physiologic significance, deletion of hepatic ApoJ or muscle LRP2 causes insulin resistance and glucose intolerance." (PMID 32332780, 2020). "In patients with polycystic ovary syndrome and insulin resistance, pioglitazone-induced improvement of insulin action is associated with an increase in muscle ApoJ and LRP2 expression." (PMID 32332780, 2020). "Therefore, it seems likely that the cellular mechanism underlying insulin resistance induced by LRP2 deletion involves a major defect in the internalization of insulin receptor at the cell surface of muscle." (PMID 32332780, 2020). "To explore the mechanism(s) by which deletion of muscle LRP2 contributes to systemic insulin resistance, we measured the ability of insulin to activate insulin signaling in insulin-sensitive tissues of M-LRP2−/− mice." (PMID 32332780, 2020). "As LRP2 has a role of renal reabsorption for its ligands such as insulin, LRP2 variants could have an association with SUA variation with increasing insulin resistance." (PMID 24366390, 2014).
Lowe syndrome (3 papers, 2019 to 2025). "We speculate that the neurodevelopmental defects seen in Lowe syndrome might be a result of defects in the recycling of multiple cell-surface receptors, including Lrp2, required for the sensing of signals essential for neuroepithelial cell survival or for the determination of cell fate." (PMID 35979861, 2022).
lung adenocarcinoma (3 papers, 2021 to 2023). A carcinoma that arises from the lung and is characterized by the presence of malignant glandular epithelial cells. "We found that the mutation rates of TTN, PCLO, RYR3, and LRP2 in human lung adenocarcinoma were 41%, 16%, 14% and 11%, respectively, but the mutation rates of other mutant genes were <10%." (PMID 34858801, 2021). "In addition, Hmcn1 and Lrp2 were previously reported as mutated in KRASG12DTP53null mouse lung tumours and are frequently mutated in human lung adenocarcinoma (13-16% in TCGA PanCancer Atlas), but are not considered as mutational drivers." (PMID 34779486, 2022).
lung carcinoma (3 papers, 2020 to 2023). "After reviewing the literature, we found that only two lung cancer patients had LRP2 mutations, so these studies were further excluded." (PMID 35834061, 2022).
papillary renal cell carcinoma (3 papers, 2023 to 2025). A rare subtype of renal cell carcinoma, arising from the renal tubular epithelium and showing a papillary growth pattern, which typically manifests with hematuria, flank pain, palpable abdominal mass or nonspecific symptoms, such as fatigue, weight loss or fever. "Lower LRP2 was associated with dedifferentiated subtypes and poorer survival in clear-cell/papillary renal cell carcinoma, papillary thyroid carcinoma, mesothelioma, and invasive breast carcinoma, with methylation-linked repression as a plausible mechanism." (PMID 41374987, 2025). "Interestingly, low LRP2 expression was associated with tumor cell dedifferentiation and poor outcome in clear cell renal cell carcinoma, papillary renal cell carcinoma, mesothelioma, papillary thyroid carcinoma, and invasive breast carcinoma." (PMID 36980716, 2023). "Interestingly, low expression of LRP2 was associated with poor patient outcome in clear cell renal cell carcinoma, papillary renal cell carcinoma, mesothelioma, papillary thyroid carcinoma, and invasive breast carcinoma." (PMID 36980716, 2023). "LRP2 was highly expressed in cancers that arise from absorptive epithelia, such as clear cell renal cell carcinoma, papillary renal cell carcinoma, mesothelioma, invasive breast carcinoma, and papillary thyroid cancer." (PMID 36980716, 2023). "As expected, LRP2 was highly expressed in tumors that arise from absorptive epithelia, such as clear cell renal cell carcinoma, papillary renal cell carcinoma, mesothelioma, invasive breast carcinoma, and papillary thyroid cancer." (PMID 36980716, 2023). "Because we show here that high levels of LRP2 are not only observed in clear cell renal cell carcinoma, but also in papillary renal cell carcinoma, mesothelioma, and in invasive breast carcinomas, we speculate that LRP2-targeted drug delivery might be effective in some of these cancer types as well." (PMID 36980716, 2023).
Stickler syndrome (3 papers, 2015 to 2021). Stickler syndrome is an inherited vitreoretinopathy characterized by the association of ocular signs with more or less complete forms of Pierre-Robin sequence, bone disorders, and sensorineural deafness (10% of cases). "Mutations in the endocytic receptor LRP2 gene result in Donnai-Barrow (DBS) and Stickler syndromes, both characterized by HM." (PMID 26107939, 2015).
thyroid cancer (3 papers, 2021 to 2025). "Interestingly, we found that APOE correlated with CLU via LRP2 in MCODE2, and CLU and LRP2 had common predicted miRNAs, which implicated hub genes and their potential miRNAs that might affect thyroid cancer proliferation and invasion through the extracellular matrix." (PMID 33521130, 2021).